CX3CL1 (C-X3-C motif chemokine ligand 1)
Diseases named in the same sentence as CX3CL1 in open-access papers (continued):
Sharing a sentence is not in itself a finding about the gene and the disease.
infection (continued). "IL-1β has been reported to modulate various aspects of immune function including the increased expression of adhesion molecules that can promote monocyte/macrophage and neutrophil infiltration to infection sites as well as the induction of CX3CL1/Fractalkine by IECs." (PMID 33194815, 2020). "At the 30th day post-infection L. amazonensis, the effects of intrathecal (i.t.)treatments with neutralizing antibody anti-CX3CL1, etanercept (soluble TNFR2 receptor), and interleukin-1 receptor antagonist (IL-1ra) on infection-induced hyperalgesia and paw edema were assessed." (PMID 31138231, 2019). "Interestingly, when infected animals were fed with a low-protein diet in the acute or chronic phase of infection, CX3CL1 levels in the serum and cardiac homogenate were elevated." (PMID 29590257, 2018). "Moreover, the infection resulted in a sustained increase in CX3CL1 levels only in 2K1C hypertensive rats, while this chemokine returned to basal levels in Sham animals." (PMID 29590257, 2018). "Using cells only treated with IL-33 or cells only infected with HTNV as controls, the mRNA expression of IL-1β, IL-6, IL-8, CCL2, CCL20, CXCL1, CXCL2, and CX3CL1 was significantly induced in HUVECs prior to infection with HTNV (MOI = 1) for 48 h and then exposed to IL-33 (20 ng/ml) for 6 h." (PMID 25658420, 2015). "Upregulation of CX3CL1 was detected in cultured human biliary epithelial cells following infection." (PMID 23724129, 2013). "On the other hand, the expression of the chemokines CCL2 (P < 0.05), CX3CL1 (P < 0.05), and MCP-1 (P < 0.05) was significantly increased from day 3 post-infection." (PMID 37452371, 2023). "To examine the pHAECs response to infection by the two viruses, we determined the mRNA levels for RSV M as well as those of IL-6, CX3CL1, CCL7 (MCP-3), Muc5AC, and Muc5B." (PMID 31330970, 2019). "The genes, Ccl2, Ccl20, Csf1, Cx3cl1, Cxcl1, Cxcl3, Il6, Birc3, Map3k8, Nos2, Nfkb2, Tnfrsf1b, and Vcam1, played core roles in a PPI network, and interacted closely with other ones in the infection." (PMID 33042984, 2020). "The level of CX3CL1 increased similarly in 2K1C and Sham rats at 1 week post-infection compared to non-infected animals." (PMID 29590257, 2018). "We found that the expression of CX3C subfamily (CX3CL1) and the C subfamily member (XCL1) was only highly increased in the H9N2-infected mice compared to the mock control, but the expression of CCL4, CXCL1, and CXCL2 was significantly increased in both single infection groups." (PMID 33968006, 2021). "At the 30th day post-infection, single i.t. treatments with neutralizing anti-CX3CL1, etanercept, or IL-1ra inhibited hyperalgesia but not paw edema, which is in line with the notion that peripheral inputs can induce spinal cord neuroinflammation that will enhance nociception." (PMID 31138231, 2019).
neurodegenerative disease (23 papers, 2011 to 2025). A disorder of the central nervous system characterized by gradual and progressive loss of neural tissue and neurologic function. "From what has been observed from the reported literature, several questions arise: (i) is CX3CL1 the cause or consequence of the neuroinflammatory process in neurodegenerative diseases?" (PMID 37175729, 2023). "Conversely, activation of CX3CL1/CX3CR1 axis can promote neural protection not only in different inflammatory conditions but also in pathological processes leading to neurodegenerative diseases and their associated inflammation." (PMID 37818457, 2023). "Given that aging is a common risk factor for neurodegenerative diseases, investigating the roles of CX3CL1/CX3CR1 signaling during natural aging could enhance our understanding of their implications in aging-related conditions." (PMID 40822679, 2025). "CX3CL1/CX3CR1 signaling has been well established as a contributor to aging-related neurodegenerative diseases." (PMID 40822679, 2025). "Our findings show age-related changes in CX3CL1 and TGFβ, with the highest levels observed in adult mice, an age at which the early mechanisms leading to neurodegenerative disease initiate." (PMID 41373544, 2025). "Recent years have seen an increase in studies exploring the roles of CX3CL1/CX3CR1 signaling in aging-related neurodegenerative diseases, including AD and PD." (PMID 40822679, 2025). "As in previous neurodegenerative diseases, also in MS, the inflammatory cytokine CX3CL1 plays a fundamental role in the pathogenesis of the disease." (PMID 37175729, 2023). "Of particular interest in recent studies of neurodegenerative disease is the role of the chemokine fractalkine (CX3CL1, FKN) and its cognate receptor (CX3CR1)." (PMID 34408629, 2021). "Our present review summarizes the current data related to the role of the CX3CL1/CX3CR1 signaling pathways in animal models of selected neurodegenerative diseases and their potential use in the clinic." (PMID 33065974, 2020). "CX3CL1 levels fluctuate in different stages of neurodegenerative diseases and in various animal models, warranting further investigation of the mechanisms underlying microglial response to pathogenic proteins, including Tau, β-amyloid (Aβ), and α-synuclein." (PMID 22919540, 2012). "The level of plasma soluble CX3CL1 also correlates positively with disease severity and progression in human PD patients, suggesting that CX3CL1 can be used as a biomarker to differentiate between neurodegenerative diseases." (PMID 22919540, 2012). "The factors that upregulate neuronal CX3CL1 or downregulate endothelial CX3CL1 levels may offer a novel therapeutic strategy for reducing neuroinflammation in neurodegenerative disease." (PMID 40842561, 2025). "Any disruptions in the CX3CL1/CX3CR1 signaling pathway may result in the development of neurodegenerative diseases." (PMID 39766878, 2024). "However, knowledge about the role of CX3CL1 in DE, as well as in other neurodegenerative diseases, remains surprisingly incomplete and controversial." (PMID 39062768, 2024). "CX3CL1 may also be or deleterious in different models of neurodegenerative diseases, indicating that the effects of CX3CL1 may be different, according upon different degenerative stimuli." (PMID 28955220, 2017). "The CX3CL1– CX3CR1 axis may play an important role in immunoregulation in several neurodegenerative diseases such as PD, AD and ALS." (PMID 24069165, 2013). "Fluctuations in CX3CL1 levels are also observed in many neurodegenerative diseases." (PMID 22919540, 2012). "Consequently, changes in CX3CL1 could be important for the dysregulation of microglia in the age-related neurodegenerative disease." (PMID 21266082, 2011). "Studies have shown that cytokines released from neurons, including CCL2, CCL21, HMGB1, CGRP, Substance P, CX3CL1, MMP2, and MMP9, can mediate microglia activation in brain injury, neuropathic pain, or neurodegenerative diseases." (PMID 36131309, 2022).
neurodegenerative disease (continued). "CX3CL1 and CX3CR1 are normally expressed at relatively high levels in the brain but decrease during aging, and may be involved in neurodegenerative diseases." (PMID 23028885, 2012). "However, more work is also necessary to determine the role of CX3CL1 and CX3CR1 in normal physiological conditions, as well as, in models of neurodegenerative diseases." (PMID 21266082, 2011).
cardiovascular disease (18 papers, 2011 to 2025). "As such, they constitute a significant source of FKN/CX3CL1, contributing to its role in the inflammatory processes associated with cardiovascular disease progression." (PMID 38612695, 2024). "Several attempts have already been made to block the FKN/CX3CL1 axis in cardiovascular diseases and others." (PMID 38612695, 2024). "One contributing factor to the burden of cardiovascular disease in CKD is a chronic micro-inflammatory state which may include systemic activation of the CX3CL1- CX3CR1 axis." (PMID 34163473, 2021). "Moreover, this CX3CR1-CX3CL1 axis has a role in cardiovascular disease, where CX3CL1 is expressed and presented by vascular endothelial cells to mediate adhesion and then subsequent extravasation of leukocytes." (PMID 33653907, 2021). "Evidence for a pivotal role of CX3CL1 in cardiovascular disease has been provided." (PMID 24799766, 2014). "Prompted by previous research assessing the role of chemokines in cardiovascular diseases, in this review we analyze a possible role of FKN/CX3CL1 in the pathological processes leading to NO-CAD." (PMID 38612695, 2024). "The CX3CL1/CX3CR1 axis is involved in leukocyte recruitment and in the development of cardiovascular disorders." (PMID 31109070, 2019). "On the endothelium CX3CL1 production induces leucocyte arrest, and may play a role in macrophage and T-cell recruitment to growing lesion, which furthers the progression of atherosclerotic lesion development and is also suggested to mediate pathological processes in cardiovascular disease." (PMID 28881821, 2017). "However, further prospective and interventional studies are needed to evaluate the impact of the CX3CL1/CX3CR1 axis and the impact of sex on the pathogenesis of cardiovascular diseases in affected populations." (PMID 41153665, 2025). "The CX3CL1/CX3CR1 axis mediates recruitment and extravasation of CX3CR1-expressing subsets of leukocytes and plays a pivotal role in the inflammation-driven pathology of cardiovascular disease." (PMID 33411754, 2021).
renal disease (16 papers, 2009 to 2025). "CX3CR1/CX3CL1 mediates a mechanism of leukocyte capture, firm adhesion, and activation which is independent of that induced by integrins and has been implicated in the pathophysiology of several inflammatory diseases, including renal diseases, allograft rejection, and atherogenesis." (PMID 19587779, 2009). "This concise review summarizes the current knowledge and recent developments regarding CX3CR1 and CX3CL1 expressing cell types and their role of in kidney disease." (PMID 34009468, 2021). "This animal study indicated that many of the functional effects of CX3CL1 demonstrated in more acute models of renal disease are also relevant to CKD." (PMID 34163473, 2021). "The present study centered on CX3CL1 due to its marked upregulation in renal diseases." (PMID 37875838, 2023). "On the other hand, the CX3CL1/CX3CR1 axis may play a protective role against some kidney disorders." (PMID 33986961, 2021). "In the development of kidney diseases, the chemotaxis and adhesion of immune cells are facilitated by CX3CR1 and its highly selective ligand CX3CL1." (PMID 38951833, 2024). "Interestingly, the role of the CX3CL1-CX3CR1 axis has been shown to contribute to both detrimental and protective effects in various kidney diseases, and elucidating the diverse functions of CX3CL1 may be important in identifying therapeutic strategies to ameliorate renal inflammation and fibrosis." (PMID 35723372, 2022). "In previous studies, the overexpression of CX3CL1 and CX3CR1+ cells was related to renal disease with protective effects of macrophage depletion blocking CX3CR1 in an experimental study." (PMID 33986961, 2021).
neurological disorders (12 papers, 2015 to 2025). "CX3CL1/CX3CR1 signal has been extensively researched on as an important mediator of inflammatory responses in neurological diseases." (PMID 37234914, 2023). "In summary, emerging evidence suggests that the CX3CL1/CX3CR1 axis is an attractive potential therapeutic target due to its ability to control inflammation in the neurological disorders." (PMID 33065974, 2020). "After this, due to the involvement of neuroinflammation in numerous neurodegenerative processes, the potential exploitation of CX3CL1’s anti-inflammatory actions became a very interesting research field for those seeking out new therapeutic strategies applicable to different neurological diseases." (PMID 39940727, 2025). "Only CX3CL1 had a suggestive support for continuous traits in neurological disorders." (PMID 38606083, 2024). "Indeed, the various CX3CL1 forms appear in some cases to serve an anti-inflammatory role of microglia, whereas in others, they have a pro-inflammatory role, aggravating neurological disorders." (PMID 37818457, 2023). "Most importantly, several DEGs such as CX3CL1, SEMA3F, OPHN1, POLA2, MCM10 and POLD3 were found to be associated with neuronal/brain process and genome stability, that is known to be relevant during neurological disorders." (PMID 36267332, 2022). "The broader role of CX3CL1/CX3CR1 signaling in the crosstalk between neurons and glial cells in CNS structures of various neurological diseases was reviewed." (PMID 38892268, 2024). "Recently, the signaling pathway mediated by fractalkine CX3CL1 and its receptor CX3CR1 has received considerable attention as an important mediator of inflammatory responses in several neurological disorders." (PMID 33065974, 2020). "Increasing evidence has indicated that the chemokine CX3CL1 and its receptor, CX3CR1, play important roles in modulating the inflammatory response in PD and in other neurological disorders." (PMID 33065974, 2020). "CX3CL1/CX3CR1 signaling modulates microglia activation, and depending upon the type and time of injury, either protects or exacerbates neurological diseases." (PMID 26329692, 2015). "In addition, the use of human samples has demonstrated that alterations in CX3CL1 and CX3CR1 expression and synthesis are quantifiable indicators of the progression of certain neurological diseases." (PMID 39940727, 2025).
inflammation (7 papers, 2011 to 2025). Aberrant reaction of the microcirculation characterized by movement of fluid and leukocytes from the blood into extravascular tissues. "The CX3CL1 is known to mediate leukocyte chemotaxis, adhesion and survival, which causes chronic adipose inflammation, and is closely associated with T2DM." (PMID 34054797, 2021). "In conclusion, we linked CX3CL1 to the necrosome complex in pulmonary inflammation and demonstrated a pivotal role of the necrosome complex in human PMNs." (PMID 33791319, 2021). "Elevated levels of CEACAM6 have been associated with chronic inflammation and could serve as a more specific marker for immune dysregulation in UC compared to serum oncostatin M. CX3CL1, as a chemokine involved in immune cell trafficking, plays a crucial role in gastrointestinal mucosal immunity." (PMID 40115777, 2025). "Cell culture and mouse studies suggest that the G protein mimics the cytokine CX3CL1 by binding to CX3CR1 on immune cells, which is thought to cause increased pulmonary inflammation in vivo." (PMID 33600439, 2021). "In a murine model of LPS-induced acute pulmonary inflammation, we investigated the role of the chemokine CX3CL1 and its receptor, CX3CR1." (PMID 33791319, 2021). "Thus, secretion of CX3CL1 from Müller cells might contribute to chronic retinal inflammation by recruiting peripheral inflammatory cells and microglia." (PMID 34776983, 2021). "The production of lung fibroblast-derived CX3CL1 were obviously reduced by specific inhibitors of the STAT-1 transcription factor, supporting the hypothesis that lung fibroblasts are an important cellular source of CX3CL1 and may contribute to causing pulmonary inflammation and fibrosis." (PMID 30884802, 2019).
bacterial infection (5 papers, 2016 to 2025). "We also observed a similar phenotype for monocytes, where pre-treatment with individual cytokines, especially TNF-α and CX3CL1, showed increased intracellular survival upon bacterial infection." (PMID 35007290, 2022). "miR-424 has been implicated in angiogenesis regulation, and suppression of the miR-424-503 gene has been shown to promote mucosal defence in bacterial infection via CX3CL1 expression." (PMID 27764787, 2016).
heart disease (5 papers, 2014 to 2024). "Based on both basic and translational investigations, we assessed the value of the CX3CL1-formed ceRNA network for developing medicines to treat heart diseases, which provides important insights into heart diseases for basic research and drug development." (PMID 37580951, 2023). "The role of the CX3CL1 pathway in heart disease has been highly controversial due to conflicting reports on its circulating ligands and limited information regarding its functional consequences in the heart in-vivo." (PMID 34504250, 2021).
brain disorder (4 papers, 2014 to 2024). A disease affecting the brain or part of the brain. "In the CNS, CX3CL1 acts as a regulator of microglia activation in response to brain disorders or inflammation." (PMID 38674036, 2024). "Although there is a growing body of literature, which is supported by extensive studies on the role of the CX3CL1/CX3CR1 signaling pathway in brain diseases, the published results are relatively controversial." (PMID 33065974, 2020). "During the last decade, there has been a growing interest in the roles that the CX3CL1/CX3CR1 signaling pathway plays in the neuropathology of a diverse array of brain disorders." (PMID 33065974, 2020). "In this review we focus on the experimental evidence of CX3CL1 involvement in neuroprotection and survey the common molecular and cellular mechanisms described in different brain diseases." (PMID 25152714, 2014). "Taken together, these data demonstrate that CX3CL1 attenuates inflammatory cytokine production, strongly modulating the neuroprotective activity of microglia in several brain diseases." (PMID 25152714, 2014). "Hence, the aim of this review is to provide a summary of the literature on the emerging role of CX3CL1 in animal models of some brain disorders." (PMID 33065974, 2020). "Nevertheless in each case insights about upstream and downstream signaling from CX3CR1/CX3CL1 have been informative and may point to new therapeutic directions for brain disease." (PMID 25152714, 2014).
cerebral artery (3 papers, 2016 to 2021). "This study reported the importance of CX3CL1 acting for transmigration of CX3CR1-positive non-classical monocytes from the blood into the human fibrotic lung in different DPLDs (HP, CTD-ILD and non-specific interstitial pneumonia)." (PMID 34208027, 2021).
metabolic disease (3 papers, 2017 to 2021). A congenital disorder (due to inherited enzyme abnormality) or acquired (due to failure of a metabolically important organ) disorder resulting from an abnormal metabolic process. "These translational strategies hold promise for future studies targeting the CX3CL1/CX3CR1 axis to treat inflammation associated with metabolic diseases." (PMID 28396851, 2017).
proliferative retinopathy (3 papers, 2013 to 2022). "The evidence that CD11b+ cells in the retina of diabetic mice have increased CX3R1 expression and the upregulation of CX3CL1 in the vitreous of mice with OIR suggest that this chemokine plays a pathogenic role in certain retinopathies." (PMID 26710229, 2015). "The classic example of a diabetic complication with increased defective angiogenesis mediated by CX3CL1 with the inflammatory background is proliferative retinopathy." (PMID 23956503, 2013).
vasculopathy (3 papers, 2013 to 2024). "There was no significant vascular or peri-vascular staining of CX3CL1 from or surrounding vessels with or without a vasculopathy." (PMID 30457999, 2018). "However, in another study, no significant perivascular or vascular CX3CL1 staining from adjacent vessels with or without vasculopathy was observed." (PMID 39392260, 2024).
CX3CL1 also shares sentences with these, for which no sentence is quoted: acute kidney injury (5 papers); Crohn disease (5); idiopathic pulmonary fibrosis (5); hyperlipidemia (4); adenocarcinoma (3); autism (3); immune diseases (3); Parkinson (3); polymyositis (3); Alcohol (2); autoimmune hepatitis (2); Autoimmunity (2); cervical cancer (2); Cirrhosis (2); glaucoma (2); hearing loss (2); infectious disease (2); Iron deficiency (2); Myocardial fibrosis (2); oligodendroglioma (2); Pain (2); retinal disease (2); scleroderma (2); subarachnoid hemorrhage (2); temporal lobe epilepsy (2); transient cerebral ischemia (2); alcoholic steatohepatitis (1); all (1); anemia (1); aneurysm (1).